U6 (U6 spliceosomal RNA )
Synonyms: LOC124900887
Gene: Small nuclear RNA gene on chromosome 4 (70,848,136 to 70,848,218, reverse strand). Ensembl gene ENSG00000283313.
Gene Ontology:
Molecular function: U4 snRNA binding
Biological process: formation of quadruple SL/U4/U5/U6 snRNP; spliceosomal tri-snRNP complex assembly
Cellular component: U4/U6 x U5 tri-snRNP complex; U6 snRNP
Homologues: Orthologues: chimpanzee U6 (99% identical), macaque U6 (94% identical), dog U6 (76% identical), rabbit U6 (75% identical), guinea pig U6 (67% identical). Paralogues in human: RNU6-812P (83% identical), RNU6-1075P (82% identical), RNU6-1316P (82% identical), RNU6-188P (82% identical), RNU6-208P (82% identical), RNU6-228P (82% identical), RNU6-409P (82% identical), RNU6-46P (82% identical), RNU6-836P (82% identical), RNU6-83P (82% identical), RNU6-934P (82% identical), RNU6-939P (82% identical), and 1287 more.